SP7 (Sp7 transcription factor)
Diseases named in the same sentence as SP7 in open-access papers (continued):
Sharing a sentence is not in itself a finding about the gene and the disease.
tumor (11 papers, 2020 to 2026). "GSEA was used to explore the METABRIC microarray data for enrichment of genes in the curated hallmarks of cancer gene sets in high and low SP7 expressing tumours." (PMID 40192943, 2025). "SP7 is a critical factor for osteoblast maturation and has been shown to have anti-tumor activity in murine OS." (PMID 37491298, 2023). "Collectively, these data indicate that Sp7 marks cells of both mesenchymal and hematopoietic origin to support the development of tumor promoting populations." (PMID 32755539, 2020). "In conclusion, we demonstrate that Sp7 is expressed in a subset of tumor infiltrating mesenchymal cells with CAF and osteogenic cell features." (PMID 32755539, 2020). "Surprisingly, Sp7 expression is also found in hematopoietic precursors, and marks tumor infiltrating immune populations enriched in immune suppressive markers." (PMID 32755539, 2020). "GSEA identified enrichment of genes involved in KRAS signaling in tumours with high SP7 expression." (PMID 40192943, 2025). "Strikingly, Sp7-Dkk1cKO mice showed a significant reduction in primary tumor growth." (PMID 38659818, 2024). "Among the top features were also other fibroblast-associated TF like SP7, RUNX2, and DLX5, which could suggest CAF-mediated collagen production at the tumor site." (PMID 39161957, 2024). "To validate expression of Sp7 in CAFs from primary tumors, we orthotopically injected B16-F10 or PyMT cells in 8 week old WT mice and the CAFs were isolated as the adherent fraction of a single cell suspension of the tumor mass." (PMID 32755539, 2020). "Thus, for the first time we show that subsets of HSCs express the transcription factor Sp7, giving rise to tumor infiltrating immune populations." (PMID 32755539, 2020). "•Stromal cells expressing the transduction factor osterix/sp7 produce fibronectin that acts on a5b1 integrin and/or TLR4 on neighboring fibroblasts to modulate Ly6G+ immune cells and suppress early tumor growth." (PMID 40592236, 2025). "SP7 mRNA expression was analysed in the METABRIC patient cohort, which has limited overlap of patient tumours assessed within the tissue microarray." (PMID 40192943, 2025). "We show that bone marrow stromal cells that do not express CD31 and CD105 are able to suppress tumor growth, and the subpopulation that expresses osterix/sp7 produces fibronectin that mediates this inhibition in vivo." (PMID 40592236, 2025). "SP1, SP4, SP7, and SP8, linked to suboptimal or partial chemotherapy responses, exhibited a predominant tumor cell presence (data not displayed)." (PMID 38975339, 2024). "We detected Sp7 expression only in CAFs but not in the tumor cell lines nor in the non-adherent fraction of the single cell suspension from the tumor mass." (PMID 32755539, 2020). "Real-Time PCR confirmed Sp7 expression in TdTOSX+ cells but not in the TdTOSX– fraction, which includes the remaining stroma and the tumor cells." (PMID 32755539, 2020). "Importantly, RT-PCR of isolated HSCs from the bone marrow of 7–8 week old wild-type naïve mice showed Sp7 expression compared to the TdTOSX- fraction isolated from the tumor mass, used as negative control." (PMID 32755539, 2020).
skeletal diseases (4 papers, 2021 to 2023). "To avoid perpetuating eponym-based nomenclature and to move toward etiology-based nomenclature, we propose the term, SP7-associated high-turnover bone disorder, for this unique phenotype." (PMID 35121733, 2022). "Here the authors show that deletion of Sp7, a gene linked to rare and common skeletal disease, in mature osteoblasts and osteocytes causes severe defects in osteocyte dendrites." (PMID 34725346, 2021). "According to previous studies, Sp7 (Osterix) knockout induces an abnormal bone morphogenesis phenotype and immature osteocytes in mice and is also associated with human skeletal diseases." (PMID 37440917, 2023). "Sp7-dependent osteocyte gene networks are associated with human skeletal diseases." (PMID 34725346, 2021). "The critical role of SP7 in the skeleton is supported by its relevance to human skeletal diseases." (PMID 35628456, 2022).
cancer (2 papers, 2017 to 2025). A tumor composed of atypical neoplastic, often pleomorphic cells that invade other tissues. "GSEA identified that high expression of SP7 mRNA is linked with genes down-regulated by K-Ras activation in the hallmarks of cancer gene sets." (PMID 40192943, 2025). "Within the list of top differentially expressed genes, in the UCHL1 KDs we found downregulation of the Wnt targets POSTN, SP7, and DLL1, of the transporter ABCA4, of the homeobox gene DLX4, and of genes recently linked to cancer progression ACTA2, AQ4, GRAP2, and ALK." (PMID 28472177, 2017).
SP7 also shares sentences with these, for which no sentence is quoted: invasive breast carcinoma (3 papers); juvenile Paget disease (2); skeletal dysplasia (2); Cirrhosis (1); collagenopathies (1); developmental delay (1); head and neck squamous cell carcinoma (1); Hypotrichosis 13 (1); lymph node metastasis (1); soft tissue sarcoma (1); type 2 diabetes (1); uremia (1).